KRT6B (keratin 6B)
Diseases named in the same sentence as KRT6B in open-access papers (continued):
Sharing a sentence is not in itself a finding about the gene and the disease.
tumor (21 papers, 2017 to 2026). "The results showed that high expression of KRT6B was positively associated with tumour invasiveness and T stage of BLCA, suggesting that KRT6B played an essential role in the progression of BLCA." (PMID 35794606, 2022). "ITGA2hi‐PTC cells were increased in PPTC samples and exhibited high expression of ITGA2, KRT6A, SOSTDC1, KRT6B, and KRT14, genes associated with tumor progression." (PMID 40985182, 2025). "KRT6B and KRT6A, members of the keratin gene family, are closely associated with clinical stage, tumor infiltration, and metastasis in patients." (PMID 40092988, 2025). "The concentration of KRT6B protein was higher in the tumor samples of the p16(+) group than in the p16(−) group (2.43711 (0.59399–4.0252) vs. 0.31389 (0.17382–0.62325)); (p = 0.0327)." (PMID 39000463, 2024). "We observed major genetic alterations in PCK1, SHC2, and KRT6B, emphasizing the role of these genes in tumor behavior modification as well as the response to treatment." (PMID 38791477, 2024). "The median protein concentration of KRT6B in the tumor was higher in HPV(+) patients than in the group of HPV(−) (2.43711 (0.59399–4.02520) vs. 0.36460 (0.16355–0.60257)); (p = 0.0335)." (PMID 39000463, 2024). "There was no observed correlation between KRT6 proteins and the amount of cigarettes per day or with years of smoking but there was a medium positive correlation of KRT6B protein in tumor samples with pack-years (0.32; p = 0.0407)." (PMID 39000463, 2024). "Our study reported that smokers showed significantly increased concentrations of KRT6A in the tumor samples and significantly decreased concentrations of KRT6B in the margin tissue." (PMID 39000463, 2024). "We found that KRT6B was significantly overexpressed in tumour tissues of BLCA patients compared with healthy controls." (PMID 35794606, 2022). "To explore the potential role of KRT6B in the tumour microenvironment of BLCA, we first utilized the EMTome database and CIBERSORT algorithm to show the landscape of immune cell infiltration in BLCA from TCGA data." (PMID 35794606, 2022). "To evaluate clinical relevance, we examined these genes in a human public dataset and found that ITGB1 and KRT6B expression in BC patient tumor samples are positively correlated with tumor grade." (PMID 31092844, 2019). "SPRR1B is co-expressed with keratin genes (KRT14, KRT6B), which may promote tumor invasion by regulating EMT." (PMID 40568599, 2025). "Moreover, we found an association between KRT6B and KRT6C concentration and proliferative index Ki-67 and HPV status in tumor samples." (PMID 39000463, 2024). "Moreover, we reported the increased concentration of KRT6B protein in the tumor and the margin samples of regular alcohol drinkers compared to occasional drinkers." (PMID 39000463, 2024). "Furthermore, regular alcohol drinkers had higher levels of KRT6B, compared to occasional drinkers 0.88750 (0.47487–1.78950) vs. 0.32989 (0.16330–0.62059); (p = 0.0047) in the tumor." (PMID 39000463, 2024). "Besides the differential expression of KRT5 and KRT19 between the margin and tumor center, KRT6B, KRT8, KRT10, and KRT17 were identified among the proteins differentiating the cancer from control tissue." (PMID 35512017, 2022). "Additionally, the results of the clinical correlation analysis showed that the expression of KRT6B was closely related to clinical stage, tumour invasion, and metastasis in BLCA patients." (PMID 35794606, 2022). "Our study showed that the median protein concentrations of KRT6B and KRT6C were higher in HPV(+) patients than in the group of HPV(−) in tumor tissues." (PMID 39000463, 2024). "The differential gene expression levels between tumor and adjacent tissue displayed in the box plot showed that LAMB3, KRT14, KRT16, KRT17, and KRT6B expression levels were significantly (p < 0.001) higher in normal tissues than in tumors." (PMID 36293530, 2022).
tumor (continued). "The differential expression between tumor and adjacent tissues expression levels displayed for KRT14, KRT16, KRT17, and KRT6B indicated that their expression levels were higher in normal tissues than in tumors." (PMID 36293530, 2022). "The increased levels of KRT6B and KRT6C proteins in the tumor margin observed in our study might therefore indicate that these proteins may affect the immune response and the immune microenvironment." (PMID 39000463, 2024). "Moreover, we found a similar correlation in the case of p16 status, where we obtained higher levels of KRT6B and KRT6C proteins in p16-positive tumor samples." (PMID 39000463, 2024). "Due to the role of KRT6 proteins in cell growth, invasion, and migration processes, it is hypothesized that the levels of KRT6A, KRT6B, and KRT6C will be changed in tumor samples compared to margin samples in patients with HNSCC." (PMID 39000463, 2024). "Comparing the bulk transcriptome profiles of the TD and nonTD patients, the TD patients exhibited upregulation of keratins (KRT81, KRT6B, KRT15, KRT5) and kallikreins (KLK5, KLK6, KLK7), indicating active extracellular matrix (ECM) remodeling and tumor expansion." (PMID 39664386, 2024). "This evidence suggests that KRT6B may be involved in the progression of BLCA, especially the transformation from noninvasive to invasive tumours." (PMID 35794606, 2022). "In our study, we found that KRT6B was involved in regulating EMT and tumour immunity in BLCA." (PMID 35794606, 2022). "Interestingly, although OS is a tumor of mesenchymal origin, upregulated genes in MG-OKS cells included epithelial-related genes, such as small proline-rich protein 2A (SPRR2A), SPRR1A, keratin 6A (KRT6A), and keratin 6B (KRT6B)." (PMID 33008481, 2020). "Genes up-regulated in cells from tumor specimens grown under CRC culture conditions are enriched with markers for lung basal cells such as TP63 (> 60 fold), podoplanin (PDPN, > 36 fold), cytokeratin genes KRT6A (> 729 fold), KRT6B (> 98 fold), and adhesion molecules LGALS7B (> 200 fold)." (PMID 28052041, 2017). "Therefore, we suggested that the upregulation of KRT6B and KRT6C protein levels in the tumor and margin samples of regular alcohol drinkers, compared to occasional drinkers, could be related to increased keratinization, in response to the tissue damage caused by alcohol and its metabolites." (PMID 39000463, 2024). "Compared to that of the paired normal tissues, the mRNA expression levels of KRT6A and KRT6B, but not that of KRT6C, were significantly increased in the paired tumor tissues." (PMID 38398015, 2024).
cancer (18 papers, 2015 to 2025). A tumor composed of atypical neoplastic, often pleomorphic cells that invade other tissues. "Wet lab experiments validated the role of KRT6B in NSCLC, demonstrating that KRT6B expression is elevated and it stimulates the proliferation of cancer cells." (PMID 40092988, 2025). "We also found that KRT6B was variously expressed in patients with different histological subtypes, molecular subtypes, metastasis statuses, and individual cancer stages of BLCA through the UALCAN website." (PMID 35794606, 2022). "KRT6B regulates EMT and cytoskeletal dynamics, which were found to support cancer cell migration, proliferation, invasion, and metastasis." (PMID 38791477, 2024). "The heat map shows positive correlation between GJB2 and the five genes (GJB6, KRT6A, KRT6B, KRT14, and IVL) in pan-cancer." (PMID 37427102, 2023). "We found that the cancer subtype markers (GRP, CHGB, NEUROD1, and CHGA for NET; KRT5, DSC3, KRT6B, TP63, and KRT6A for SCC; and NKX2-1, KRT7, NAPSA, and MUC1 for ADC) were specifically expressed in the corresponding cancer subtypes." (PMID 35962452, 2022). "Subpopulation B consisted of 121 cells (29.1%) and showed overexpression of 13 genes, including seven cancer genes (HSPB1, ANXA1, SLPI, KRT8, KRT19, KLK7, and ABL2) and several Keratin genes (KRT8, KRT7, KRT19, and KRT6B)." (PMID 28794488, 2017).
infection (1 paper, 2015). The state of being infected such as from the introduction of a foreign agent such as serum, vaccine, antigenic substance or organism. "This was accompanied by an increase in the frequency of proliferating basal keratinocytes (Krt 14+ Ki67+), both in the hair follicle and interfollicular epidermis, and an increase in Krt6b expression in whole epidermal tissue, indicating that infection initiates the keratinocyte activation cycle." (PMID 25575749, 2015).
skin disorder (1 paper, 2018). Any deviation from the normal structure or function of the skin or subcutaneous tissue that is manifested by a characteristic set of symptoms and signs. "Since abnormal expression of KRT6B and KRT17 may affect their structural role in the epidermis, these proteins might represent a biomarker for skin disorders." (PMID 30061793, 2018).
KRT6B also shares sentences with these, for which no sentence is quoted: lung adenocarcinoma (4 papers); Palmoplantar keratoderma (4); bladder tumors (2); cutaneous melanoma (2); epidermolysis bullosa simplex (2); lung squamous cell carcinoma (2); Nail dystrophy (2); adenocarcinoma (1); Amoebiasis (1); bladder urothelial carcinoma (1); Deep Venous Thrombosis (1); diabetic cardiomyopathy (1); duodenal adenocarcinoma (1); epidermolytic ichthyosis (1); epidermolytic palmoplantar keratoderma (1); metastatic melanoma (1); painful (1); periodontitis (1); serous ovarian cancer (1); squamous cell carcinoma (1); staphylococcus aureus infection (1); superficial epidermolytic ichthyosis (1); urothelial cell carcinomas (1).